CCND1 (cyclin D1)
Diseases named in the same sentence as CCND1 in open-access papers (continued):
Sharing a sentence is not in itself a finding about the gene and the disease.
cancer (continued). "Taken together, our cohort of multiparous MMTV-cyclin D1 mice was less potent in promoting mammary hyperplasias and carcinomas as has previously been shown and MMTV-cortactin did not accelerate the incidence of hyperplasia or MG tumors in bitransgenic mice." (PMID 16536875, 2006). "Thus, we speculated that circDCP2 upregulates the CCND1 expression level by directly binding to HnRNPA2B1, thereby activating the PI3K-AKT pathway and promoting cancer progression." (PMID 40770637, 2025). "Additionally, miR-146b may influence Cyclin D1 and C-MYC expression, further contributing to the proliferative and invasive properties of cancer cells." (PMID 40224178, 2025). "Moreover, acting as the upstream activator of Cyclin D1, C-MYC may elicit the transformation of cancer cells." (PMID 40224178, 2025). "This indicates that in certain cases, CCND1 amplification does not necessarily coincide with CDKN2A loss, implying that these two mechanisms may independently contribute to cancer progression." (PMID 40702169, 2025). "For example, an interaction between Cyclin D1 (CCND1)and members of the PI3K complex was lost in cancer cells, while aninteraction between fibroblast growth factor receptor 3 (FGFR3) andDaple (CCDC88C) was gained in cancer cells and activated cell migratoryproteins." (PMID 38556766, 2024). "Differentiation-inducing factors, originally found in Dictyostelium discoideum, and their derivatives possess strong antiproliferative activity, at least in part by reducing cyclin D1 expression in various cancer cells, but their effects on PD-L1/PD-L2 have not been examined." (PMID 38854456, 2023). "It should be noted that, according to the information reported by the cBioPortal for cancer genomics, the human RB1 gene, as well as the genes encoding CDK4 (CDK4), CDK6 (CDK6), and cyclin D1 (CCND1), are all expressed in AGS and MCF-7 cells, without mutations reported so far." (PMID 37298236, 2023). "In addition, various other cancers, including pancreatic ductal adenocarcinoma, non-small cell lung cancer (NSCLC), and melanoma, frequently show cyclin D1 overexpression and amplification, which emphasizes the potential use of CDK4/6 inhibitors in their treatment." (PMID 36675501, 2023). "Although, the mechanism of D. villosa cancer inhibition may not have been achieved through cyclin D1 expression, the excellent display of IC50 may be considered." (PMID 36840116, 2023). "Both in vitro and in vivo studies have consistently confirmed the anti-cancer potential of fucoidan via the inhibition of angiogenesis, induction of cell cycle arrest and apoptosis and down regulation of CDK4, cyclin D1 and cyclin D2 in cancer cells [reviewed in more details in and]." (PMID 36874031, 2023). "In contrast, the expression level of miR-19a in human cancer specimens was significantly lower than that found in adjacent non-cancerous tissue, which might play an inhibitory role for HCC progression by targeting cyclin D1." (PMID 38003232, 2023). "Genes upregulated by >1.5‐fold in cancer tissues rather than in normal intestinal mucosae include Wnt signaling‐related genes such as Fzd1 (fold change [FC], 5.6), Myc (FC, 2.6), Ccnd1 (FC, 1.6), Mmp2 (FC, 10.4), Mmp7 (FC, 16.0), Mmp8 (FC, 12.9), Mmp12 (FC, 52.2), and Spp1 (FC, 149.3)." (PMID 35274815, 2022). "Likewise, icodextrin did not significantly alter the expression of cyclin B1 or cyclin D1 in a time-dependent manner in either cancer cell line." (PMID 35334562, 2022). "Therefore, not surprisingly, cyclin D1 overexpression potentially plays a role in cancer development and progression." (PMID 34206989, 2021).
cancer (continued). "It was shown that PZH’s anti-cancer activities might be related to the suppression of STAT3 signaling pathways, therefore resulting in the upregulation of Bax/Bcl-2 ratios as well as down-regulation of CCND1 and CDK4 expression." (PMID 33658028, 2021). "Saha and co-workers observed that cancer prostate cell lines (human PC3; DU145; LNCaP and murine HMVP2) treated with 6-shogaol, showed decreased levels of several signal transducer and activator of transcription 3 (STAT3) and NF-κB-regulated target genes including cyclin D1." (PMID 34202966, 2021). "Among them, Cyclin D1 and CDK6 play a vital role in the G0/G1 phase, therefore the inhibition of Cyclin D1 and CDK6 could be considered as a promising strategy for the treatment of cancers." (PMID 34572904, 2021). "Cyclin D1, a member of the cyclin family (D1, D2, and D3) which functions as a regulatory subunit and forms a complex with CDK4 or CDK6 for regulating cell cycle transition from the G1 to S phase, is frequently overexpressed in cancer cells and dysregulates CDK activity." (PMID 31840737, 2020). "Therefore, downregulation or inhibition of Chk1, Chk2, cyclin D1, and CDK6 could be an innovative target for cancer treatment." (PMID 32010609, 2019). "The effects of SHetA2 on molecular endpoints in cancer cells are much greater than its effects in healthy cells, which translates into the lack of observed toxicity, however differential effects on cyclin D1 specifically have not yet been evaluated." (PMID 29273857, 2018). "Cyclin D1 may serve as a pharmacodynamic biomarker for drug action or toxicity based on its differential regulation by SHetA2 in cancer over non-cancer cells." (PMID 29273857, 2018). "From these previous reports, Pin1 may also play a role for PKM2 translocation to the nucleus in OSCC, and cell cycle progression by cyclin D1 expression through nuclear PKM2 and β-catenin binding may also be one of the mechanisms of cancer cell progression in OSCC progression." (PMID 30333907, 2018). "The expression of cyclin D1 is expected to be low or absent in most of the other cell cycle phases, although cancer cells may show aberrant regulation." (PMID 29716531, 2018). "Moreover, OCT4 promoted cyclin D1 (CCND1) expression and activated cyclin-dependent kinase 4/6 (CDK4/6) activity to accelerate cell cycle progression and promote the proliferation and division of cancer cells." (PMID 29069758, 2017). "Excessive CCND1 expression with or without biological activity is common in human cancers." (PMID 28380465, 2017). "Also in MDA-MB-231 and SK-MEL-28 cells, which showed relatively higher IC50 values than other cancer cells, sesaminol treatment did not reduce cyclin D1 expression." (PMID 28368390, 2017). "Collectively, our findings supports the hypothesis that activation of the ATM/AKT/GSK-3β signaling pathway leading to CDK4/CDK6/cyclin D1 overexpression plays a key role in LDR-induced hormesis, and is responsible for the difference of hormesis induced by LDR in normal and cancer cells." (PMID 27708248, 2016). "Thus, the investigation of the molecular mechanism by which PF down-regulates cyclin D1 and CDK4 expression may be required to understand how to better treat cancer and even to develop better anti-cancer drugs." (PMID 27670681, 2016). "However, the exact mechanism of Cyclin D1 inhibition in berberine-treated cancer cells has not been well documented." (PMID 27854312, 2016).
cancer (continued). "In addition to the inflammation pathway, several cancer-related pathways were identified from the global NSAIDs-regulating miRNA-gene subnetwork, including cell cycle (CDK6, CCND1, CCKN1A, and E2F1), proliferation (MYC), apoptosis (BCL2) and angiogenesis (VEGFA)." (PMID 27329603, 2016). "To investigate whether TFF1-dependent suppression of H. pylori-induced transcriptional activation of β-catenin leads to downregulation of β-catenin downstream targets, we assessed mRNA and protein expression of cyclin D1 and c-Myc in an in vitro MKN28 cancer cell model." (PMID 25980439, 2015). "Furthermore, it has been revealed that cell cyle factors such as cyclin D1 and cyclin B1 was downregulated by ZFX knockdown in multiple cancer types, which might account for the cell cycle disruption in Tca-8113 cells treated with ZFX-siRNA." (PMID 25916205, 2015). "Indeed we found that SDE-genes identified in previous step are related to STAT3 pathways including genes involved in cell cycle progression (Cyclin D1, D2, and c-Myc), cell survival (Bcl-xL, Bcl-2, Mcl-1), angiogenesis (HIF1α, VEGF), cancer inflammation (NF-KB, IL-6)." (PMID 26056083, 2015). "After confirming ADAM10 downregulation by western blot analysis, blots were reprobed with c-Myc, cyclin D1 as well as CD44, all of which showed reduction in ADAM10 depleted cells, indicating that ADAM10 regulates catenin-dependent intracellular signaling in the cancer cells." (PMID 26440150, 2015). "Endothelin-1 (ET-1) has been involved in many cancer-related processes, such as proliferation, angiogenesis, EMT and metastasis, many of these exerted through activation of multiple signaling cascades, including the Wnt/β-catenin pathway and its known targets such as cyclin D1, MMP2 and survivin." (PMID 26543229, 2015). "Although extensive further work is needed to draw a definitive link, it is tempting to speculate that this disruption might affect the expression of downstream clock-controlled genes regulating the cell cycle (such as Cyclin D1 and Wee1), contributing to tumorigenesis in HPV-related cancers." (PMID 24728990, 2014). "Endogenous cyclin D1 mRNA expression level without treatment was higher in HSC-3 cells and MG-63 cells than in other cancer cells (Hela cells) and HEK293 cells, suggesting that efficiency of sgRNA targeting of cyclin D1 may depend upon the endogenous cyclin D1 expression levels." (PMID 25437003, 2014). "Concomitantly, Cyclin-D1, that was negative in low and high grade dysplastic lesions, was up-regulated in neoplastic lesions (IS and, even more, in K) vs NM, with a maximum value in advanced carcinoma (red bars in the graphs)." (PMID 24657851, 2014). "Since cyclin D1 is an important regulator of G1 to S-phase during the cell cycle, ART induced degradation of this protein may be sufficient to arrest cell growth in some cancers." (PMID 23516601, 2013). "Genetically engineered mouse models were used to determine whether or not ERα over-expression demonstrated cooperativity with cyclin D1 over-expression in cancer development, reaction to the chemical carcinogen DMBA, or tamoxifen response." (PMID 24575359, 2012). "Overexpression of cyclin D1 has a positive correlation with receptor status and non-basal carcinomas suggesting that cyclin D1 expression might be a marker of good prognosis." (PMID 19615042, 2009). "The experiments with cyclin D1-deregulated cells showed that curcumin did not alter cyclin D1 expression level in cancer cells, but in normal cells, where cyclin D1 expression is tightly regulated by mitogenic signaling, its expression is inhibited by curcumin." (PMID 18834508, 2008). "In addition, FZC18 turns off cyclin D1 in CRC and HCC cancer cell lines." (PMID 18382662, 2008). "In addition, curcumin was found to inhibit the association of cyclin D1 with CDK4/CDK6 or phosphorylation of pRb in some cancer cells where the expression of cyclin D1 is not deregulated and thus arrest them at G0/G1 phase." (PMID 18834508, 2008).
cancer (continued). "Importantly, a number of human cancer cell lines with high cyclin D1 levels were shown not to express αB crystallin." (PMID 17407548, 2007). "Because of our novel finding that cyclin D1 promotes pyrimidine synthesis, we wondered whether combined inhibition of its main kinase partner (Cdk4) along with the downstream pyrimidine synthesis enzyme dihydroorotate dehydrogenase (DHODH) would synergistically block cancer cell growth." (PMID 38152849, 2023). "Furthermore, the anti-cancer effects of capsaicin have been demonstrated by the inhibition of Epidermal Growth Factor Receptor (EGFR) and PI3K/Akt/mTOR signaling pathways, and through IL-6/Signal Transducer and Activator of Transcription- 3 (STAT-3)/Cyclin D1 (CCND1) and survivin pathways." (PMID 35600864, 2022). "Among SE target genes that are not CRC TFs, CCND1, encoding the cyclin D1 and often dysregulated in various types of cancer, turned out to be essential across NB cell lines, including both MES and ADRN NB cells, and to be significantly overexpressed across NB cells compared to other cancer cells." (PMID 35277192, 2022). "Moreover, PZH has been found to block the G1/S cell cycle progression and to suppress both mRNA and protein levels of CCND1 and CDK4 in Caco-2 CRC cells, suggesting that inhibition of cell proliferation via cell cycle arrest is a potential MOA through which PZH exerts its anti-cancer effecs." (PMID 33658028, 2021). "Redox-mediated activation of IRE1α and ATF6α may support dormant cancer cell survival, while activating PERK phosphorylates eukaryotic initiation factor 2α (eIF2α) and inhibiting its translation of cyclin-dependent kinases (CDK4), Cyclin D1/D3, leading to quiescence of dormant cancer cells." (PMID 34685686, 2021). "Thus, cyclin D1 reduction in non-cancerous tissue as a surrogate for cancerous tissue is likely to provide an underestimate of the anti-cancer drug effect, and may provide an estimate of potential toxicity." (PMID 29273857, 2018). "Furthermore, in cancer cell lines with mutations in both KRAS and PIK3CA, MEK inhibitor could not induce the cell cycle arrest due to the sustained cyclin D1 expression." (PMID 26121043, 2015). "Furthermore, cyclin D1 (CCND1), CDK1 and CDK6 mRNA levels were significantly higher in CRC compared to normal children samples, which may be related to the uncontrolled cellular proliferation in cancer." (PMID 24098334, 2013). "Moreover, Dyrk1B has been reported to control cyclin D1 levels in HeLa cells treated with differentiation-inducing factor-3 (DIF-3) by affecting DIF-3-induced cyclin D1 phosphorylation and degradation, in the lung epithelial cell line Mv1Lu and in different cancer cell lines." (PMID 24312406, 2013). "However, it is not clear whether the GABA receptor regulates CCND1 in cancer." (PMID 40145254, 2025). "Binding of eIF4G to CCND1 mRNA was reduced by INK128 treatment in Cal27 but not in HN12, which suggests cancer heterogeneity in this response and a more general impact on CCNE1." (PMID 38954773, 2024).
cancer (continued). "Interestingly, our results showed that the expression levels of CDK4, CDK6, and cyclin D1 in CRC cells were visually reduced after POLQ knockdown, which suggested that POLQ knockdown affects the cell cycle process and may be a potential factor in cancer therapy." (PMID 39520627, 2024). "Even though the ecDNA landscapes of the three cancer cell types were not the same, we identified several ecDNA hotspots, such as the oncogene MYC, CDK4 and CCND1 genomic loci." (PMID 37517066, 2023). "Compared with placebo control, bosentan treatment did not significantly change the mRNA levels of Cyclin D1, MMP2, Vimentin and ETB under conditions of fibrocyte depletion, except leading to a slight downregulation of mRNA expression of ETA in cancer cells." (PMID 36241617, 2022). "TA had no consistent effect on ERK or AKT phosphorylation, Cyclin D1 or Cyclin B1 levels, or PARP or Caspase 3 cleavage across the MDA-MB-468, BT474, and WM793 human cancer cell lines." (PMID 35095503, 2021). "Using combined pan-cancer studies, moderately positive correlations of CCT2 mRNA were found with MYC, CDK2, CDK4, CCNE1 but not CCND1 (slight negative correlation)." (PMID 33996588, 2021). "In BrCa, this combined analysis indicated that the events are related to CCND1 amplifications, despite the frequent events in sizeable genes TEMN4 and SHANK2 of which their fusion transcripts are not driving cancer." (PMID 34891161, 2021). "Unlike in other cancer cells, the expression of cyclin D1 in MCL is neither regulated by EGLN2/PHD1 nor by FOXO3A; thus, the molecular mechanism controlling cyclin D1 production and degradation in MCL remains to be elucidated." (PMID 31517438, 2019). "The inhibition of PCNA, cyclin D1 and HSPA5 expression by this combination is encouraging as a means to preferentially target cancer cells without affecting normal cells." (PMID 30218018, 2018). "Furthermore, the differential effect of SHetA2 on cancer over non-cancer tissues supports the potential of dietary doses below 250 mg/kg/day (1000 ppm) altering cyclin D1 in pre-cancerous and cancerous tissues, even though they did not reduce cyclin D1 protein in normal cervical tissue." (PMID 29273857, 2018). "We found that the expression ratio of CCND1 to CDKN2A clearly classified RB1-positive and -negative cancer lines, the predictive accuracy of which was superior to that of individual CDKN2A or CCND1, respectively." (PMID 21447152, 2011). "This deeply conserved putative enhancer element could regulate CCND1 in both humans and mice, opening the possibility of studying MYEOV regulatory functions in cancer using non-primate animal models." (PMID 39139450, 2024). "This suggests that during cancer formation, SHANK2 is selected independent of Cyclin D1." (PMID 32661924, 2021). "miR-133a-3p may have a key role in mechanisms that lead to either cancer (target genes CDKN1A, and CCND1) or non-cancerous (target gene EDN1, and CXCL2) conditions secondary to smoking." (PMID 34440025, 2021). "However, our data showed that CCND1, an important partner of CDK4/6, is not strongly correlated with HCC patient survival or anti-cancer drug response." (PMID 31349793, 2019).